HMGB2 (high mobility group box 2)
Diseases named in the same sentence as HMGB2 in open-access papers (continued):
Sharing a sentence is not in itself a finding about the gene and the disease.
cancer (52 papers, 2013 to 2026). A tumor composed of atypical neoplastic, often pleomorphic cells that invade other tissues. "HMGB2 is frequently overexpressed in various cancers and is often associated with poor clinical outcomes." (PMID 41280896, 2025). "Previous studies have linked HMGB2 to the development and progression of several cancers by influences cell proliferation, apoptosis, and metastasis through antiapoptotic pathways." (PMID 39247201, 2024). "High HMGB2 expression is associated with a poor prognosis for the patient, as it promotes cell proliferation and glycolysis in cancer cells." (PMID 37176041, 2023). "In NSCLC, the high expression of HMGB2 in cancer was associated with the chemotherapy response and poor prognosis." (PMID 35962344, 2022). "Previous studies have identified HMGB2 as an oncogene that is associated with the poor prognosis of various cancers, including hepatocellular carcinoma, breast cancer and NSCLC." (PMID 35525959, 2022). "High-mobility group box 2 (HMGB2) is implicated in tumorigenesis in various cancers." (PMID 29463261, 2018). "The frequency of mutations and copy number alterations (CNA) in genes encoding HMGB1 and HMGB2 proteins were analyzed as well as in those genes encoding proteins detected in the Y2H search associated with PCa, using the open platform for exploring cancer genomics data, c-Bioportal." (PMID 31694235, 2019). "Radioresistance arises from cancer stem cell maintenance (CD133/HMGB2), TAM polarization (CSF-1R/CD44), and enhanced homologous recombination (RAD51)." (PMID 42125691, 2026). "Our results demonstrated that HMGB2 knockdown significantly inhibits cancer cell proliferation, migration, and invasion across multiple female-specific cancers." (PMID 40396172, 2025). "The observed reduction in phagocytosis highlights HMGB2’s potential as a modulator of macrophage-mediated immune responses in cancer." (PMID 40396172, 2025). "Our results provide compelling evidence that HMGB2 plays a crucial role in maintaining macrophage phagocytic activity, particularly in the context of female-specific cancers." (PMID 40396172, 2025). "Shared pseudotemporally correlated genes between both integrated datasets included genes associated with proliferation (CENPF and TOP2A), cancer‐associated fibroblasts (DCN and COL1A1) and neurodevelopment (HMGB2 and NPAS3)." (PMID 39836549, 2025). "HMGB2 knockdown reduced cell proliferation in all tested cancer types, as demonstrated by CCK-8 and EdU assays." (PMID 40396172, 2025). "In this study, we investigated the role of HMGB2 in macrophage-mediated phagocytosis across several cancer types." (PMID 40396172, 2025). "HMGB2 plays a crucial role in regulating cell cycle progression, particularly at the G1/S and G2/M transitions, which are essential checkpoints in cancer proliferation." (PMID 40396172, 2025). "In breast (MDA-MB-231, T47D), cervical (SiHa, HeLa), ovarian (SKOV3, OVCAR3), and endometrial (Ishikawa, RL95-2) cancers, HMGB2 knockdown consistently reduced migratory and invasive capacities." (PMID 40396172, 2025). "This study highlights the pivotal role of phagocytosis regulators, particularly HMGB2, in the progression of female-specific cancers." (PMID 40396172, 2025). "HMGB2 knockdown significantly inhibited the migration and invasion of cancer cells, as shown by Transwell assays across multiple female-specific cancer types." (PMID 40396172, 2025). "For example, volasertib can cause downregulated BCL2L1 expression, disrupt the interaction between PLK1 and NEK7, or displacement of HMGB2 from mitotic chromosomes, thereby affecting mitotic arrest and apoptosis in cancer cells." (PMID 39872221, 2025). "HMGB2 knockdown significantly inhibited cancer cell proliferation, migration, and invasion in female-specific cancers." (PMID 40396172, 2025). "Incubation of cancer cells with cell targeted (CT)-HMGB2 confirmed that HMGB2 is responsible for translocation of CRT to the plasma membrane." (PMID 38496553, 2024).
cancer (continued). "In this regard, in the future, HMGB2 can be considered as a biomarker of the early stages of cancer, which helps to assess severity of the disease, predict the effectiveness of treatment and patient survival." (PMID 37176041, 2023). "Given the effect of HMGB2 on stem cell pluripotency, the suppression or neutralization of HMGB2 appear to be an option for eliminating cancer stem cells and preventing the development of secondary tumors." (PMID 37176041, 2023). "In this review, we focus on the structural and functional properties of HMGB2 protein, as well as on its role in cancer and autoimmune diseases." (PMID 37176041, 2023). "Yet, in some types of cancer (e.g., melanoma), HMGB2 promotes cell proliferation and invasion through the interaction with β-catenin." (PMID 37176041, 2023). "HMGB2 is overexpressed in highly proliferative tissues, including various types of cancer, and is downregulated in senescent cells and tissues." (PMID 37176041, 2023). "The results revealed that the cancer cell subclusters c8_TOP2A, c9_HMGB2, c12_MKI67, and c13_TK1 were dominantly in a cycling state, while c1_TCN1, c2_CD74, c3_CD24, c5_CEACAM6, and c10_SAT1 were mainly in a quiescent state." (PMID 36529697, 2023). "Several authors have concluded that HMGB2 is largely involved in processes of inflammation and cancer development, as well as in the response of the immune system to these processes." (PMID 37176041, 2023). "In recent years, HMGB2 has been shown to be overexpressed in various cancers, including pancreatic cancer, melanoma, and BC." (PMID 35114890, 2022). "Mechanistically, circ_UBAP2 exerts a cancer-promoting effect on OS by downregulating miR-637 and upregulating the expression of HMGB2." (PMID 35114890, 2022). "HMGB1 showed a positive association with CDK1 (R = 0.51), SSRP1 (R = 0.57), H2AFV (R = 0.53), and HMGB2 (R = 0.57) genes in several cancer types and these data were visualized as a heatmap." (PMID 36230798, 2022). "Recent literature has indicated that the expression of HMGB2 is elevated in various human cancers, suggesting that the small heterodimer partner represses HMGB2 by recruiting or repressing E2F1 activity." (PMID 34408262, 2021). "Beyond the controversy of HMGB1, the roles of HMGB2/3 in cancers are unclear, especially in the context of the tumor immune microenvironment (TIME)." (PMID 34777483, 2021). "The well-studied members in this subfamily, including HMGB1 and HMGB2, exhibited important functions in various cancer progression." (PMID 33842327, 2021). "From the outset, we found that HMGBs were significantly up-expressed in various TCGA cancers, except that HMGB2/3 were down-expressed in LAML." (PMID 34777483, 2021). "Interactome targets of HMGB1 or HMGB2 that have been identified in our Y2H study were previously found to be related to cancer hallmarks, and are also dysregulated in PCa, as confirmed by detection of changes in mRNA or protein levels." (PMID 31694235, 2019). "Despite extensive characterization of the diverse roles of HMGB1 in cancer, much less is known about the signaling pathways of HMGB2, especially its relevance in carcinogenesis." (PMID 29463261, 2018). "Although HMGB1 has been studied more extensively, considerably less is known regarding HMGB2 in the study of cancer, particularly its relevance in carcinogenesis." (PMID 23426143, 2013). "In conclusion, our data revealed that the expression levels of HMGB1 and HMGB2 were highly increased in BCa, and that HMGB1/HMGB2 overexpression was significantly correlated with malignant tumor progression and angiogenesis." (PMID 23426143, 2013). "Although there has been extensive characterization of the various roles of HMGB1 in cancer, considerably less is known regarding the involvement of HMGB2 in carcinogenesis, including its angiogenic effects and precise signaling pathways." (PMID 23426143, 2013).
cancer (continued). "Targeting HMGB2, either alone or in combination with cell cycle inhibitors, metabolic inhibitors, or immunotherapy, represents a promising strategy for improving outcomes in female-specific cancers." (PMID 40396172, 2025). "We found a previously unidentified role for HMGB2 in the differentiation and survival of functional memory and exhausted T cells, with vast implications for secondary reinfections and immunotherapies to cancer and chronic viruses." (PMID 37704621, 2023). "Previous studies have confirmed the oncogenic role of HMGB2 in various cancers, but the biological functions of HMGB2-derived circRNAs remain unknown." (PMID 35525959, 2022). "Previous studies have confirmed the oncogenic role of HMGB2 in various cancers." (PMID 35525959, 2022). "HMGB2 is reported to be involved in the progression of many types of cancers, including NSCLC." (PMID 35525959, 2022). "We further demonstrated that the anti-cancer effect of CENPU exhibited a HMGB2-dependent manner." (PMID 34872447, 2021). "Further the results showed that the anti-cancer effect of CENPU was HMGB2-dependent." (PMID 34872447, 2021). "HMGB1 and HMGB2 not only differently affect the cellular activity of telomerase in etoposide-untreated or -treated hESCs and hNECs, but the proteins also differentially modulate the sensitivity of cancer cells to distinct anticancer drugs." (PMID 33076532, 2020). "Our recent findings on the distinct modulation of cellular activity of telomerase by HMGB1 and HMGB2 could be a starting point for developing new approaches aiming at the promotion of cell death in drug-treated cancer cells." (PMID 33076532, 2020). "In cancer cells (and refs. therein), the HMGB2 protein could function as a positive regulator of telomerase activity." (PMID 33076532, 2020). "HMGB1 and HMGB2 are members of the High Mobility Group (HMG) protein superfamily that contain a DNA binding domain (HMG-Box), and their overexpression has been associated to main cancer hallmarks, tumor progression, metastasis formation and bad prognosis." (PMID 29721183, 2018). "Compared with the other genes, ATG12 and HMGB2 were more related to chemoresistance of cancer." (PMID 25996293, 2015). "The significant reduction in both phagocytic activity and cell proliferation upon HMGB2 knockdown suggests that HMGB2 could serve as a promising therapeutic target, not only for modulating immune responses but also for enhancing the efficacy of cancer treatments." (PMID 40396172, 2025). "Inhibition of HMGB1 and HMGB2 secretion and/or their activation of nuclear factor-kappa B (NF-kB) has potential utility for treating cardiovascular, and neurodegenerative diseases; whereas CT-HMGB2 could augment therapeutic approaches to cancer treatment." (PMID 38496553, 2024). "Additionally, high expression of HMGB2 correlates with metastasis and, in some cases, with a decrease in sensitivity to certain anticancer drugs, such as cisplatin, leading to a resistance of cancer cells to chemotherapy and poor prognosis." (PMID 37176041, 2023). "Protein-level analyses in nine cancer types revealed decreased expression of PLCB4, SOD3, and THRA, alongside increased expression of HMGB2 and RAC2, relative to normal tissues." (PMID 40852729, 2025). "Among these genes, seven proteins (MAP2K1, FERMT2, HMGB2, FAF2, STK26, THRAP3, and KRT15) showed significant differences between carcinoma and adjacent tissues (TCGA-HNSC database)." (PMID 39319867, 2025). "Therefore, combining HMGB2 modulation with anti-PD-1/anti-PD-L1 therapy may enhance and preserve Tpex differentiation and increase clinical efficacy in the settings of chronic infections and cancer." (PMID 37704621, 2023). "Integrating the results of two steps of survival analyses, high expression of HMGBs suggested unfavorable prognosis in the following cancers: HMGB1 in ACC; HMGB2 in ACC, KIRP, LGG, LIHC, MESO; and HMGB3 in BRCA, ESCA, SARC, and SKCM." (PMID 34777483, 2021).
cancer (continued). "High-mobility group box 2 (HMGB2) binding protein interacts with MIEN1 and enhances cancer progression and proliferation." (PMID 35582722, 2019). "For example, chemoresistant cancer cell line SGC7901/VCR develops upon exposure to vincristine and exhibits increased autophagy, which is regulated by Atg12 and high-mobility group box 2 (HMGB2)." (PMID 28646911, 2017). "For instance, HMGB1, HMGB2, and MS4A1 were hypomethylated and highly expressed, whereas hypermethylation of genes such as LDB1, NDUFS2, and POU2F2 led to their reduced expression, reinforcing the impact of DNA methylation on gene dysregulation in cancer." (PMID 40396172, 2025). "High mobility group box 2 (HMGB2) mRNA is ac4C‐modified by NAT10, and binding of eukaryotic translation elongation factor 2 (EEF2) to NAT10 increases HMGB2 expression and promotes cancer proliferation." (PMID 40448344, 2025). "Here, several growth-associated genes were up-regulated, including RNA helicase (HELLS), PRR11, CDCA8, and DNA topoisomerase 2 (TOP2A), HMGB2, EIF2B4, and CDKN3, which are thought to serve important functions during growth stimulation, many of which are known to be up-regulated in various cancers." (PMID 37907238, 2024). "The objective of this study is to better understand the role of HMGB1 and HMGB2 in aggressive PCa cancers not responding to hormonal treatment, identifying genes differentially regulated." (PMID 38542079, 2024). "Considering the high homology of HMGB2 compared to HMGB1, it might have a similar role in the development of cancer." (PMID 33407071, 2021). "In addition, elevated HMGB expression indicated clinicopathological advances in these cancers: HMGB1 in ACC, HNSC, and ESCA; HMGB2 in ACC, HNSC, KIRC, LGG, and LIHC; and HMGB3 in ESCA and HNSC." (PMID 34777483, 2021). "Besides, significant positive correlations between the expression of HMGBs and ICP genes were found in the following cancers: HMGB1 in HNSC, LIHC, PAAD, and PRAD and HMGB2 in HNSC, KIRC, KIRP, LGG, LIHC, PRAD, THCA, and SKCM." (PMID 34777483, 2021). "Integrating the significance of prognosis, TIICs, ICP genes, and MSI and (or) TMB, we induced that HMGBs might be promising immunological targets for the following cancers: HMGB1 for ACC and KIRC; HMGB2 for ACC and LGG; and HMGB3 for BRAC, SARC, SKCM, and OV." (PMID 34777483, 2021). "HMGB2 up-expression indicated elevated infiltration of Th2 cells and MDSCs and (or) ICP gene expression in ACC, KIRP, LGG, LIHC, and MESO, with medium to strong correlation strength, which might partly explain the poor survival of patients with these cancers." (PMID 34777483, 2021). "Thus, the nuclear abundance of HMGB1 (and likely also of HMGB2) can be seen as a marker for proliferative capacity: Senescent cells have essentially no nuclear HMGBs, while continuously dividing cancer cells display levels even higher than those seen in normal tissue." (PMID 34166567, 2021). "The expression levels of EP400, HMGB2, CDK1, PPARG, and MVK were found to be significantly correlated with HMGA1 expression level in both analyzed cancer subtypes but not in non-cancerous tissue of the lung." (PMID 35805937, 2022). "Although the proteins identified in the study, as well as HMGB1 and HMGB2, had been previously and independently related to EOC, the implication of a direct interaction with HMGB proteins, as part of their mechanism of action in cancer progression, had not been previously envisaged." (PMID 32867128, 2020).
infection (6 papers, 2019 to 2024). The state of being infected such as from the introduction of a foreign agent such as serum, vaccine, antigenic substance or organism. "To investigate T cell responses within the same host, we next co-transferred small numbers (1×103 each) of congenically marked WT and Hmgb2−/− P14 T cells at a 1:1 ratio into congenically mismatched WT mice, followed by Arm infection." (PMID 37704621, 2023). "We co-transferred WT and Hmgb2−/− P14 T cells at a 1:1 ratio into WT mice, followed by Arm or Cl13 infection." (PMID 37704621, 2023). "We next evaluated the frequencies of Tpex and Tex cells by measuring TCF-1 and TIM-3 expression of tumoral WT and Hmgb2−/− P14 T cells and found significantly less Hmgb2−/− Tpex cells compared to WT, similar to our findings during Cl13 infection." (PMID 37704621, 2023). "We observed significantly decreased frequencies of Hmgb2−/− Tpex cells during Cl13 infection, and since these cells drive the limited reinvigoration of exhausted T cells after secondary infections, we next examined whether exhausted Hmgb2−/− CD8+ T cells could respond to Arm infection." (PMID 37704621, 2023). "Principal component analysis (PCA) showed the type of infection accounted for transcriptional differences across PC1 (47% variance), while Hmgb2 expression accounted for transcriptional changes across PC2 (30% variance)." (PMID 37704621, 2023). "In Hmgb2−/− mice, we also found similar and even higher frequencies of TCF-1+ cells in Hmgb2−/− CD8+, GP33-41, GP276-286, and NP396–404 T cells compared to WT mice during Cl13 infection." (PMID 37704621, 2023). "The ISD bait method was validated by identifying known dsDNA sensors including HMGB1, HMGB2, and HMGB3, components of the AIM2 inflammasome, and the SET complex that plays a role in HIV-1 retroviral detection and infection." (PMID 33042865, 2020). "By contrast, HMGB2-depletion had no detectable impact on IFNB1 accumulation induced in response to infection with VSV, an RNA virus, in agreement with reports showing HMGB2 was dispensable for IFNB1 induction by RNA in murine cells." (PMID 31841110, 2019). "Although we did not evaluate the response of Hmgb2−/− Tpex cells to anti-PD-1/anti-PD-L1 blockade, we observed a defect in their reinvigoration with secondary Arm infection." (PMID 37704621, 2023). "Here, we found HMGB2, a paralog of HMGB1, to be upregulated at 7 DPC in Afg09 infection." (PMID 34615921, 2021). "However, despite similar phenotypes and initial responses of exhausted WT and Hmgb2−/− P14 T cells, Hmgb2−/− P14 T cells drastically declined after 8dpi Cl13 infection and did not persist." (PMID 37704621, 2023). "Additionally, although Hmgb2−/− Tmem cells had high expression of the transcription factor TCF-1, a critical regulator for memory T cell transcriptional programs and Tcm-mediated recall responses, they were still unable to persist and respond to secondary infection." (PMID 37704621, 2023).
adenocarcinoma (3 papers, 2016 to 2024). A common cancer characterized by the presence of malignant glandular cells. "The data show that mutations and CNA affecting HMGB1, HMGB2, and the proteins identified in the corresponding Y2H interactome are more frequently present in neuroendocrine PCa and castration-resistant PCa than in adenocarcinoma." (PMID 31694235, 2019). "The clinical relevance of HMGB1 and HMGB2 in the regulation of identified genes was explored in public databases comparing gene expression in PCa patient samples classified as adenocarcinoma or neuroendocrine types." (PMID 38542079, 2024). "However, quantitative differences in the expression of Tk1, Top2a, Hmgb2, Rrm2, Kpna2, and H1fx were observed and were found to be strongly up-regulated in small-sized adenocarcinomas." (PMID 27602772, 2016). "We selected several oncogenes and one tumor suppressor gene, showing deregulation by HMGB proteins, for independent validation after HMGB1 or HMGB2 shRNA silencing or overexpression in PC-3, considered the model of SCNC PCa, and in the LNCaP cell line, considered the adenocarcinoma model." (PMID 38542079, 2024).
cardiovascular diseases (3 papers, 2022). "Studies show that there is a relationship between HMGB2 and cardiovascular diseases in cardiac myocytes." (PMID 35159393, 2022).
bacterial infection (1 paper, 2025). "HMGB2, a chromatin-associated protein linked to DNA repair and immune activation, was downregulated, further suggesting altered immune readiness and resistance to bacterial infection." (PMID 41050709, 2025).